CD4 (CD4 molecule)
Diseases named in the same sentence as CD4 in open-access papers (continued):
Sharing a sentence is not in itself a finding about the gene and the disease.
Sepsis (continued). "Also, mice with T-cell-specific TSC1 deletion had lower expression of T-bet and CD4+ T cell count indicating that the expression of T-bet required mTOR to participate in the regulation, and the regulation affected the CD4+ T cell count in Candida sepsis." (PMID 32431684, 2020). "Considering that mouse studies have shown lymphocytes in tissues are less susceptible to sepsis-induced alterations, similar shifts in CD4 T cell subset representation may not be observed in peripheral tissues of humans." (PMID 32733454, 2020). "In addition, the effects of sepsis on the ability to produce effector cytokines (IL-10 in the case of Treg) may be less severe for Treg than for other CD4 T cell subsets." (PMID 32733454, 2020). "Thus, the specific decrease of CD4+ T cells that we observed in our study (with blood drawn 48 to 72 h after diagnosis of sepsis) may also relate to an impaired recovery of CD4+ T cells and not a selective decrease." (PMID 32825352, 2020). "Moreover, the different recovery rates between the memory and regulatory Foxp3+ CD4 T cell populations could suggest additional time-dependent mechanisms that control the ability of sepsis survivors to respond to secondary infection." (PMID 32903436, 2020). "A thorough understanding of how sepsis impacts CD4 T cells based on previous studies and new models that accurately reflect the human immune system may improve translational value of research aimed at restoring CD4 T cell-mediated immunity, and overall immune fitness following sepsis." (PMID 32733454, 2020). "In contrast, the 2D2 cells in the post-transfer experiments were only influenced by the sepsis-induced changes in the environment, such as reduced DC function, reduced capacity to traffic across endothelium, and alterations in the proportion of regulatory CD4 and CD8 T cells." (PMID 33191915, 2020). "In our manuscript, we demonstrated that Mdivi-1 reduces apoptosis in CD4+ T cells during sepsis and balancing mitochondrial fusion-fission and preventing ER stress are two potential mechanisms involved in the protective effect of Mdivi-1 on CD4+ T cells in sepsis." (PMID 31263382, 2019). "However the results of this study clearly link delayed activation of CD4+Th17 lymphocytes with sepsis in elderly humans and provide biomarkers for the occurrence of sepsis in the elderly that have the potential to inform subsequent studies of immune modulation in elderly patients with sepsis." (PMID 31658288, 2019). "Additionally, to further explore whether preventing ER stress is a mechanism involved in the protective role of Mdivi-1 on CD4+ T cells in sepsis, we used tunicamycin to induce ER stress and 4-PBA to alleviate ER stress." (PMID 31263382, 2019). "Thus, the increased expression of apoptosis inducing proteins at the early time point (day 1) of sepsis might lead to CD4 T cell apoptosis in the spleen as reported in our previous study." (PMID 30052667, 2018). "Additionally, we were able to evaluate the sepsis-induced numerical and phenotypic changes in endogenous Ag-specific CD4 T cells and B cells (2W1S:I-Ab- and PE-specific, respectively) responding to the same foreign Ag (2W1S peptide covalently coupled to PE in CFA)." (PMID 30429857, 2018). "In human sepsis, the majority of data obtained on the role of leukocyte subsets in sepsis is confined to the peripheral blood, focusing primarily on the role of the immune-suppressing CD4+CD25+Foxp3+ regulatory T cells (Tregs), impaired monocyte HLA-DR expression, and lymphocyte apoptosis." (PMID 30174555, 2018). "Thus, ghrelin treatment markedly restored CD4 T cell proliferation in the spleen during sepsis." (PMID 30052667, 2018). "However, the frequency of the 1B11+ CD4+ T cells was significantly increased at 120 hr post sepsis." (PMID 30226896, 2018). "Thus, ghrelin benefits sepsis partially through the restoration of CD4 T cell proliferation." (PMID 30052667, 2018).
Sepsis (continued). "Other prospective clinical studies have shown that increased monocyte PD-L1 expression on days 3–4 after sepsis serves as an independent predictor of 28-day mortality in septic shock patients, and septic patients also demonstrated increased expression of PD-1 on CD4+ and CD8+ T lymphocytes." (PMID 29135922, 2017). "Therefore, we hypothesized that HSYA may inhibit CD4+ T lymphocyte apoptosis by regulating proteins in intrinsic mitochondrial pathway during sepsis." (PMID 28932195, 2017). "Since FTY720 is a functional inhibitor of multiple S1P receptors, further studies using selective receptor antagonists are required to clarify whether the expansion of the CD4+ T cells and CD4+ pDCs in the bone marrow during sepsis occurs through the same S1P signaling pathway." (PMID 29218051, 2017). "Hence, we hypothesized that Mfn2 might be involved in the regulation of CD4+ T cell apoptosis in sepsis and autophagy might be the potential mechanism." (PMID 29358849, 2017). "Therefore, 2B4 could be a novel therapeutic target during sepsis and further studies are needed to discover the signaling mechanisms downstream of 2B4 in CD4+ T cell during sepsis." (PMID 29135922, 2017). "Consequently, we demonstrated the kinetics of autophagy in T cells during sepsis, crosstalk between autophagy and apoptosis, mitochondrial accumulation by deficiency of autophagy, and augmented interleukin (IL)-10 production by CD4+ T cells lacking autophagy." (PMID 27618275, 2017). "To compare whether reduced NK cell levels in the peripheral blood and sustained NK cell levels in the BAL fluid are comparable with other lymphocytic subset levels, also described as lymphopenic in sepsis, we performed additional staining to determine T CD4 and T CD8 cell levels in the same samples." (PMID 28287491, 2017). "However, IL-15 SA treatment failed to prevent burn wound sepsis-induced loss of CD4+, CD8+, B, NK and NKT cells and failed to improve bacterial clearance and survival." (PMID 26859674, 2016). "Thus, IL-37-activated CD4+CD25+ Tregs might be advantageous to control the early inflammatory response in sepsis in vivo." (PMID 27941849, 2016). "Finally, CD3E down-regulation may indicate that antigen recognition may be uncoupled during sepsis in CD4+ T lymphocytes and T-cells." (PMID 27180802, 2016). "Therefore, in the early stage of sepsis, the percentage of BTLA+/CD4+T cells may contribute to the risk stratification for sepsis." (PMID 26329820, 2015). "Additionally, the percentage of BTLA+/CD4+T cells was lower in non-survivors than in survivors, and it was associated with 28-day mortality in patients with sepsis." (PMID 26329820, 2015). "Moreover, mice lacking Atg7 in T lymphocytes showed an increase in sepsis-induced mortality, T cell apoptosis and loss of CD4+ and CD8+ T cells, in comparison to control mice." (PMID 25029098, 2014). "• Lack of BTLA protected primary and secondary lymphoid organs from cellular apoptosis, and this was associated with the loss of CD4+ T cells and B cells following CLP in mice, suggesting that BTLA may be directly involved in CD4+ T-cell apoptosis during experimental sepsis." (PMID 24289156, 2013). "Here we find that an increase in the percentage of BTLA+CD4+ T cells is much higher in the patients that develop subsequent nosocomial infections, thus implicating BTLA as a possible biomarker for identifying which critically ill patients are most susceptible to the development of sepsis." (PMID 24289156, 2013). "More CD4+ T lymphocytes may help patients with severe sepsis to survive." (PMID 23670410, 2013). "The inability of post-septic CD4+ T cells to commit to either the TH1 or TH2 lineage may be significant for survivors of severe sepsis, especially in regards to secondary infections of the lung which require a directed cytokine response for clearance of the invading microorganism." (PMID 21655295, 2011).
Sepsis (continued). "Analysis of immune cell infiltration revealed significant positive correlations between RORA and counts of CD4 + T, CD8 + T, and NK cells in sepsis." (PMID 42096424, 2026). "The absolute counts of lymphocytes (Lym), CD3+ T cells, CD4+ T cells, and CD8+ T cells were significantly lower in sepsis patients compared to HD." (PMID 40642098, 2025). "This study found significantly higher infiltration of M0 macrophages, neutrophils, and regulatory T cells, and relatively lower infiltration of activated NK cells, resting memory CD4+ T cells, naïve CD4+ T cells, and CD8+ T cells in neonates with sepsis." (PMID 41424725, 2025). "Compared to HD, sepsis patients exhibited markedly reduced absolute counts of Lym, CD3+ T cells, CD4+ T cells, and CD8+ T cells, as well as decreased B% and NK%." (PMID 40642098, 2025). "Many researches found CD4+ and CD8+T cells are diminished and that the amount, phenotype, and function of B cells are changed in sepsis." (PMID 40909263, 2025). "The observed depletion of memory CD4+ T cells in patients with sepsis is consistent with the higher expression of DPP4 in these cells, supporting its potential role in sepsis progression." (PMID 40124361, 2025). "A recent pediatric study found more TEMRA CD4+ T cells in sepsis patients, which is comparable to our finding of more TEMRA CD8+ T cells in sepsis." (PMID 39935482, 2025). "The percentage of circulating CD4+ T lymphocytes expressing LC3II and CHOP were significantly higher in elderly sepsis patients (71.1% versus 38.7%, P=0.003; 95.5% versus 81.1%, P=0.004)." (PMID 40933998, 2025). "In this clinical study we found that elderly sepsis patients had significantly lower lymphocyte count, CD4+ T lymphocyte count and CD8+ T lymphocyte counts, along with enhanced ERS on CD4+ T cell." (PMID 40933998, 2025). "Immune-related parameters such as CD4+ and CD8+ counts varied among patients, likely due to differences in infection timing and immune status, as sepsis-induced immunosuppression progresses dynamically." (PMID 40421209, 2025). "Despite evidence of interactions between CD4+ and CD8+ T-cell subsets, such interactions occurred in restricted communication modules in sepsis." (PMID 40433376, 2025). "This study reveals the molecular network basis of sepsis immune heterogeneity, identifying MMP9 as a key regulator of CD4+ T cell exhaustion." (PMID 41306770, 2025). "These cells were also less functional in sepsis: after stimulating PBMC’s ex vivo with PMA/Io, only healthy samples had a statistically significant reduction in CD4+IL10+ T cells." (PMID 39935482, 2025). "The infiltration level of CD4+ T cells (r = −0.741, P < .0001), CD8+ T cells (r = −0.82, P < .0001), and TFH (r = −0.856, P < .0001) were negatively correlated with sepsis." (PMID 40184094, 2025). "In this context, the present study aims to establish a predictive model for the occurrence of SAE in sepsis patients based on the combination of IFN-γ, TNF-α and the CD4+/CD8+ ratio." (PMID 41189156, 2025). "Our study revealed a significant reduction in the abundance of CD4 and CD8 lymphocytes in pediatric sepsis samples." (PMID 40070882, 2025). "TIM-3+CD4+ T cells show reduced proliferative ability and elevated expression of inhibitory markers compared to TIM-3-CD4+ T cells, and conditional deletion of TIM-3 in CD4+ T cells reduces mortality in response to sepsis." (PMID 40364841, 2025). "Testing lymphocyte counts at different time points revealed that absolute counts of CD3+ T cells, CD4+ T cells, and CD8+ T cells were consistently lower in the sepsis group across all time intervals." (PMID 40642098, 2025). "The absolute counts of lymphocytes (Lym), CD3+ T cells, CD4+ T cells, and CD8+ T cells were significantly lower in the sepsis group compared to the HD group." (PMID 40642098, 2025). "Age was inversely correlated with the percent of naïve (CCR7+/CD45RA+) CD4+ T cells in AOD (r2 = 0.49, p=0.008) and sepsis (r2 = 0.19, p=0.024)." (PMID 39935482, 2025).
Sepsis (continued). "Here, we initially discovered that cell surface ENO1 on CD4+ T cells acted as a receptor anchored by NET-MPO, facilitating NET accumulation around CD4+ T cells and recruiting IFITM2 as a DNA sensor in sepsis-induced immunosuppression." (PMID 40892462, 2025). "Experiments using the mouse cecum ligation and perforation (CLP) model have demonstrated diminished responses in naïve and memory CD4+ T and CD8+ T cells in sepsis survivors, increasing their vulnerability to new or recurrent infections." (PMID 39981259, 2025). "In sepsis patients, apoptosis levels of CD4+ and CD8+ T cells, B cells, and DCs are markedly elevated, and the functions of CD4+ T helper 1 (Th1), Th2, and Th17 cells are reduced." (PMID 40817040, 2025). "Longitudinal analysis further revealed that CD3+, CD4+, and CD8+ T cell counts remained lower in sepsis patients than in healthy controls at all time points during the early phase of the disease." (PMID 40642098, 2025). "Both CD4 helper T cells and CD8+ cytotoxic T cells are inactivated and downregulated in patients with sepsis." (PMID 40699834, 2025). "To further delineate the effects of sepsis on PLN T cells in MLDS T1D, we determined the number of CD4+ and CD8+ T cells able to produce IFN-γ, IL-17, TNF and IL-10 in CLP+STZ and SHM+STZ mice." (PMID 41142792, 2025). "Consistent with our findings, they found an increased proportion of CD14+ monocytes and decreased proportions of CD4+ T cells, CD8+ T cells, NK cells and mDC cells in sepsis." (PMID 40486505, 2025). "In contrast, the sepsis group displayed lower expression levels of three immune cell markers: CD8 T cells, resting memory CD4 T cells, and activated memory CD4 T cells." (PMID 40070882, 2025). "Moreover, significant elevation in PANoptosis and decreased immune function of CD4+ T lymphocytes were observed in the peripheral blood of septic patients, suggesting a pathophysiological axis linking ribophagy-mediated cell death to lymphocyte dysfunction in sepsis." (PMID 40995563, 2025). "Further analysis of the correlation between sepsis feature genes and immune cells revealed that CLU, GLPX, and CKAP4 were negatively correlated with CD4 naive T cells, while DPEP2 and BCL11B were positively correlated." (PMID 41359645, 2025). "There were less central memory (CCR7+/CD45RA-) CD4+ and CD8+ T cells in sepsis compared to healthy (p=0.02 and 0.04, respectively)." (PMID 39935482, 2025). "Previous research has shown that exhaustion of CD4 T cells and CD8 T cells indicates poor prognosis in sepsis patients." (PMID 40065471, 2025). "In contrast, subcutaneous infection led to increased IL-10+ B cells, CD4+, CD8+ T cells, and MHCII+ macrophages, all correlating with the sepsis score." (PMID 40178612, 2025). "Using human and animal samples, we have demonstrated that NLRP6 is upregulated in multiple cell types, including CD4 and CD8 T cells in the spleen during sepsis." (PMID 38720893, 2024). "For cellular immunity, the numbers of both CD4+ and CD8+ T cells showed a progressive decrease from HCs to bacteremia and sepsis patients, whereas the frequency of activated HLA-DR+CD8+ T cells tended to be higher in bacteremia and sepsis patients versus HCs." (PMID 38707899, 2024). "Like CD4+T cells, the increased apoptosis of CD8+T cells during sepsis is another main mechanism of immunosuppression in sepsis, and is correlated with mortality." (PMID 38669099, 2024). "As the severity of sepsis escalated, levels of CD3+, CD4+, and CD4+/CD8+ correspondingly diminished in the 3 patient groups, while IL-6 and PCT levels exhibited a positive correlation with sepsis severity." (PMID 39465765, 2024). "Although many groups have reported skewing of CD4+ TFH subsets in a virus-specific context, there are substantial gaps in the literature in the case of bacterial infections and sepsis." (PMID 38197178, 2024). "In sepsis, EGFR can induce the apoptosis of CD4 + T lymphocytes by promoting the Warburg effect through TBK1/Glut1 signaling pathway." (PMID 38632608, 2024).
Sepsis (continued). "Mechanistically, we identified that, in sepsis, the Akt/mTOR/SREBP2 signaling pathway is augmented in naive CD4+ T cells, promoting cholesterol metabolism and facilitating Treg differentiation and functionality." (PMID 38888975, 2024). "The percentage of peripherally induced naïve regulatory T cells (CD3+CD4+CD25+FOXP3+CD45RA+ CD31-) was significantly higher in neonates developing sepsis compared to another group." (PMID 39072327, 2024). "The NLRP6 KO mice showed higher numbers of CD3-, CD4- and CD8-positive T cell subsets and decreased T cell death in the spleen following sepsis." (PMID 38720893, 2024). "Another significant finding was the reduction in T‐lymphocyte subsets (CD4 Naive, CD4 T, CD8 Naive, CD8 T) in sepsis." (PMID 39578684, 2024). "Results showed that, as the sepsis severity increased, CD3+, CD4+, and CD4+/CD8+ levels decreased, while IL-6 and PCT levels rose significantly." (PMID 39201697, 2024). "A recent clinical trial demonstrated that IL-7 therapy successfully restored depleted CD4+ and CD8+ effector cells by threefold to fourfold in patients with sepsis." (PMID 39720718, 2024). "Taken together, these data uncovered that TIGIT was predominantly upregulated on CD4+ T cells, CD8+ T cells and NK cells and increased TIGIT suppressed T cell function at the initiated stage of sepsis." (PMID 38545097, 2024). "Specifically, marked apoptosis and reductions in CD4+ and CD8+ T lymphocytes occur in the early phase of sepsis." (PMID 39720718, 2024). "The KO mice showed a higher number of CD3, CD4, and CD8 positive T cell subsets and reduced T cell death in the spleen following sepsis." (PMID 38720893, 2024). "This apoptosis, particularly of CD4+ and CD8+ T-cells, results in a decrease in lymphocyte counts in late-stage sepsis patients, contributing to immunosuppression and a heightened risk of secondary infections." (PMID 39076981, 2024). "At the same time, they detected the increased proliferation of CD4+ T cells and the secretion of pro-inflammatory cytokines IFN-γ and IL-17 in sepsis patients." (PMID 38339179, 2024). "Sepsis patients with high PGK1 expression presented higher memory B cells, monocytes, resting memory CD4 T cell and lower regulatory T cells." (PMID 39712033, 2024). "The relationship between CD4+ TFH cells and B cells in sepsis remains to be thoroughly addressed, and also how the regulation of CD4+ TFH cells by CD4+ TFR cells is affected in this setting." (PMID 38197178, 2024). "At the same time, the frequency of RTE Treg (CD3+CD4+CD25+FOXP3+ CD45RA+CD31+) was considerably lower, suggesting that Treg cells are more peripherally induced in newborns developing sepsis." (PMID 39072327, 2024). "Wang established a mouse model of sepsis and found that plasma HMGB1 level was increased in mice with sepsis, while the expression of CD28 on the surface of CD4+T cells was inhibited, and the expression of PD-1 was increased." (PMID 39314628, 2024). "CIBERSORTx and ssGSEA results revealed that B cells, naive CD4 T cells, CD8 T cells, macrophages, monocytes, and neutrophils were abundant in both trauma and sepsis patients." (PMID 38384415, 2024). "CD4, CD8A, CD28, CD2, CD3E as T cell surface active molecules play important roles in the immune response process; among them, the roles of CD4 and CD8 T lymphocytes in sepsis have been widely recognized." (PMID 39654893, 2024). "When examining long-term outcomes after PMN-MDSCs treatment for early sepsis, we found PMN-MDSCs in circulation and BMCs were significantly reduced, and CD4+ and CD8+ T cells were partly elevated." (PMID 38385073, 2024). "An intriguing observation is that IL-38 upregulates the number of circulating CD4+/CD25+/FOXP3+ Treg cells in sepsis patients, possibly reflecting the host’s effort to mitigate the cytokine storm in sepsis cases." (PMID 38533512, 2024).